IGFBP7 (insulin like growth factor binding protein 7)
Diseases named in the same sentence as IGFBP7 in open-access papers (continued):
Sharing a sentence is not in itself a finding about the gene and the disease.
dementia (3 papers, 2017 to 2022). Loss of intellectual abilities interfering with an individual's social and occupational functions. "Proteins SAP3, NPS‐PLA2, IGFBP‐7, MIC‐1, TIMP‐4, and OPG have been reported to be associated with dementia in case‐control studies, and TREM2 and N‐terminal pro‐BNP in prospective cohort studies, with all associations in the same direction as in this study." (PMID 34338426, 2022). "IGFBP7, one of the seven IGFBPs identified in the mammalian genome that is used to transport and regulate the bioavailability of IGF1 and IGF2, is deregulated in PTSD and dementia via Igfbp7 promoter DNA methylation in mouse and human brains." (PMID 28670349, 2017).
endothelial dysfunction (3 papers, 2023 to 2026). In vascular diseases, endothelial dysfunction is a systemic pathological state of the endothelium (the inner lining of blood vessels) and can be broadly defined as an imbalance between vasodilating and vasoconstricting substances produced by (or acting on) the endothelium. "Higher MYBPC3 was most prognostic in HFrEF while higher ANGPT2 and IGFBP7 (endothelial dysfunction and oxidative stress) in HFpEF." (PMID 41711204, 2026). "Together, these data demonstrate that anti-IGFBP7 treatment exerts therapeutic effects on endothelial dysfunction and psoriasis-like inflammation." (PMID 36917196, 2023). "Elevated IGFBP7 drives endothelial dysfunction and skin inflammation." (PMID 36917196, 2023).
Hepatic steatosis (3 papers, 2024 to 2025). Steatosis is a term used to denote lipid accumulation within hepatocytes. "The acromegaly group had significantly lower liver steatosis (p = 0.006) and higher liver stiffness (p = 0.004), serum IGFBP7 (p = 0.048) and CK18 (p = 0.005) levels than the control group." (PMID 38709454, 2024). "Cytokeratin 18 (CK18) and insulin-like growth factor binding protein 7 (IGFBP7) increase in liver steatosis and fibrosis." (PMID 38709454, 2024).
hyperemesis gravidarum (3 papers, 2018 to 2024). Severe, intractable vomiting during pregnancy (usually the first trimester) accompanied by dehydration, weight loss, and electrolyte imbalances. "From the genetic perspective, among European women, variants in placenta and appetite genes such as GDF15 and IGFBP7 have been associated with hyperemesis gravidarum as has circulating levels of GDF15." (PMID 34420517, 2021). "Common variants of IGFBP7 are susceptibility loci for the diagnosis of pregnancy-related nausea and vomiting, with serum levels of IGFBP7 significantly increased in hyperemesis gravidarum women at 12 weeks of pregnancy." (PMID 39081862, 2024). "IGFBP7 plays a crucial role in pathological pregnancies, including complete hydatidiform mole, pregnancy-related nausea and vomiting (hyperemesis gravidarum), and endometriosis." (PMID 39081862, 2024). "In summary, IGFBP7 plays a multifaceted role in folliculogenesis, embryo implantation, pregnancy success, and pathological pregnancies, including conditions like complete hydatidiform mole, hyperemesis gravidarum, and endometriosis." (PMID 39081862, 2024).
leukemia (3 papers, 2015 to 2023). A malignant (clonal) hematologic disorder, involving hematopoietic stem cells and characterized by the presence of primitive or atypical myeloid or lymphoid cells in the bone marrow and the blood. "Similarly, in B-cell ALL IGFBP7 expression in BMSCs was found to be associated with asparaginase resistance and decreased leukemia-free survival." (PMID 25887188, 2015). "PROM1, FLT3, CTGF, LGALS1, IGFBP7, ZNRF1, and RUNX2 were found highly expressed in the MLL-R pro-B ALL compared to the other subclassification of leukemia." (PMID 36276286, 2022).
Miscarriage (3 papers, 2018 to 2025). A pregnancy that ends at a stage in which the fetus is incapable of surviving on its own, defined as the spontaneous loss of a fetus before the 22th week of pregnancy. "IGFBP7 expression is reduced in the trophoblast cells and villous tissues from unexplained recurrent spontaneous abortion patients, suggesting that the IGFBP7 promotes trophoblast invasion, a crucial process for successful pregnancy." (PMID 40867581, 2025). "Thus IGFBP7 may play roles in both miscarriage and in the severity of NVP, providing a genetic mechanism for the protective effect of NVP." (PMID 29563502, 2018).
non-small cell lung carcinoma (3 papers, 2013 to 2023). A group of at least three distinct histological types of lung cancer, including non-small cell squamous cell carcinoma, adenocarcinoma, and large cell carcinoma. "Of note, circulating levels of IGFBP7 and THBS2 have been associated with outcome in high-grade soft tissue sarcoma and non-small cell lung cancer, respectively." (PMID 27391064, 2016).
oesophageal cancer (3 papers, 2020 to 2023). "Editing of insulin-like growth factor-binding protein 7 (IGFBP7), a secreted protein associated with apoptosis and senescence, in oesophageal cancer cells, results in an amino acid change protecting the protein from proteolysis." (PMID 33050791, 2020).
osteoporosis (3 papers, 2020 to 2025). A condition of reduced bone mass, with decreased cortical thickness and a decrease in the number and size of the trabeculae of cancellous bone (but normal chemical composition), resulting in increased fracture incidence. "On the contrary, Ye and colleagues showed that IGFBP7 treatment in an ovariectomy-induced osteoporosis mouse model attenuated osteoporotic bone loss by inhibiting the activity of osteoclasts and therefore suppressed osteoporosis." (PMID 35163315, 2022). "These novel insights into IGFBP7 may facilitate the development of potential treatment strategies for oestrogen deficiency‐induced osteoporosis and other osteoclast‐related disorders." (PMID 31889368, 2020). "These novel insights into IGFBP7 may aid in developing potential treatment strategies for oestrogen deficiency‐induced osteoporosis and other osteoclast‐related disorders, although further studies are needed." (PMID 31889368, 2020). "Moreover, in a mouse ovariectomy‐induced osteoporosis model, IGFBP7 treatment attenuated osteoporotic bone loss by inhibiting osteoclast activity and enhancing osteoblast activity." (PMID 31889368, 2020). "Moreover, in a mouse ovariectomy‐induced osteoporosis model, IGFBP7 treatment attenuated osteoporotic bone loss by inhibiting osteoclast activity." (PMID 31889368, 2020). "Our results show that IGFBP7 acted as a negative regulator of osteoclastogenesis by inhibiting the NF‐κB signalling pathway and played a protective role in osteoporosis." (PMID 31889368, 2020). "Taken together, these findings show that IGFBP7 suppressed osteoclastogenesis in vitro and in vivo and suggest that IGFBP7 is a negative regulator of osteoclastogenesis and plays a protective role in osteoporosis." (PMID 31889368, 2020). "We used both in vitro and in vivo studies to investigate the effects of IGFBP7 on RANKL‐induced osteoclastogenesis and osteoporosis, together with the underlying molecular mechanisms of these processes." (PMID 31889368, 2020). "In conclusion, these findings indicate that IGFBP7 is a negative regulator of osteoclastogenesis via the NF‐κB signalling pathway and plays a protective role in osteoporosis." (PMID 31889368, 2020). "Together with our previous study, this study provides useful insight into the potential effects of IGFBP7 in regulating bone metabolism and preventing osteoporosis." (PMID 31889368, 2020). "For a better understanding of the role of IGFBP7 in bone metabolism, we used both in vitro and in vivo studies to investigate the effects of IGFBP7 on RANKL‐induced osteoclastogenesis and osteoporosis and characterized the underlying molecular mechanisms of these processes." (PMID 31889368, 2020). "The hypothesis of this study was, IGFBP7, an osteogenesis‐regulating gene that had been reported in our previous study, might play an important role in osteoclast differentiation and osteoporosis." (PMID 31889368, 2020).
psoriasis (3 papers, 2023). An autoimmune condition characterized by red, well-delineated plaques with silvery scales that are usually on the extensor surfaces and scalp. "Based on the pathogenic role of IGFBP7 in degrading the endothelial glycocalyx and aggravating skin inflammation, we further evaluated the possibility of targeting IGFBP7 to treat psoriasis." (PMID 36917196, 2023). "Our ELISA results showed a significant elevation of serum IGFBP7 in psoriasis patients, which was positively correlated with disease severity." (PMID 36917196, 2023). "More importantly, we provided evidence in a psoriasis-like mouse model that anti-IGFBP7 treatment showed promising therapeutic effects for restoring the endothelial glycocalyx and alleviating skin inflammation." (PMID 36917196, 2023). "Li, Shao, and colleagues identified degradation of the endothelial glycocalyx in psoriatic skin, and demonstrated that IGFBP7hi cells express and secrete IGFBP7 in response to psoriasis-related cytokine signaling." (PMID 37115692, 2023). "Together with our data on anti-IGFBP7 treatment in psoriasis-like mice, these findings suggest that IGFBP7 is a promising therapeutic target for psoriasis." (PMID 36917196, 2023). "Identifying a disease-specific endothelial feature (high levels of EC-secreted IGFBP7 in psoriasis) and its utilization for therapeutic intervention is a very promising strategy since it does not affect the normal EC population." (PMID 37371110, 2023). "The role of IGFBP7 in psoriasis is a particularly exciting discovery because IGFBP7 is thought to act on a different aspect of immune cell trafficking compared with the targets of similar existing therapies, efalizumab, natalizumab, and vedolizumab." (PMID 37115692, 2023). "We further showed that IGFBP7 promoted T cell adhesion to ECs by destroying the endothelial glycocalyx structure in psoriasis." (PMID 36917196, 2023). "To identify the upstream regulator of IGFBP7 expression and secretion, we first compared the transcriptional profiles between IGFBP7hi and IGFBP7lo skin ECs in psoriasis." (PMID 36917196, 2023). "As IGFBP7 is a known angiocrine factor, the authors proposed that glycocalyx destruction in psoriasis occurs in a paracrine manner." (PMID 37115692, 2023). "Blocking IGFBP7 shows promising therapeutic effects for normalizing skin vasculature and alleviating skin inflammation in psoriasis." (PMID 36917196, 2023). "Anti-IGFBP7 treatment significantly alleviated psoriasis-like skin inflammation, with reduced psoriatic scales, skin capillary dilation, erythrocyte exocytosis, epidermal thickening, keratinocyte proliferation, and mRNA levels of psoriatic cytokines and antimicrobial peptides." (PMID 36917196, 2023). "In addition, the serum level of IGFBP7 is elevated in psoriasis patients compared with healthy individuals and is positively correlated with disease severity." (PMID 36917196, 2023). "Taken together, our results depict the distinct functions of EC clusters in healthy and psoriatic skin, identify IGFBP7hi ECs as an active subset modulating vascular function and cutaneous inflammation, and indicate that targeting IGFBP7 is a potential therapeutic strategy in psoriasis." (PMID 36917196, 2023). "Moreover, our findings in a psoriasis-like mouse model support that administration of an anti-IGFBP7 antibody can be a feasible approach for normalizing skin vasculature and alleviating skin inflammation." (PMID 36917196, 2023). "Importantly, we identified a subset of skin ECs in psoriasis, namely, IGFBP7hi ECs, that overexpress and secrete IGFBP7, destroying the endothelial glycocalyx and facilitating immune-cell adhesion and extravasation." (PMID 36917196, 2023). "We also treated HMEC-1 cells with psoriasis-related cytokines such as IL-17A, IL-22, IL-25, IFN-γ, TNF-α, and, VEGF-A, and among them, IFN-γ significantly upregulated the expression and secretion of IGFBP7 in HMEC-1 cells." (PMID 36917196, 2023).
psoriasis (continued). "In addition, anti-IGFBP7 treatment, which started 3 days after IMQ modeling to mimic clinical settings, also dramatically alleviated psoriasis-like skin inflammation." (PMID 36917196, 2023).
renal dysfunction (3 papers, 2025). "MM patients exhibited renal dysfunction (low eGFR, high creatinine), hypoalbuminemia, elevated β2-microglobulin, high LDH, increased plasma cell percentage, and elevated serum amylase, along with elevated urinary biomarkers IGFBP-7 and TIMP-2, reflecting systemic and renal involvement." (PMID 40369504, 2025).
schizophrenia (3 papers, 2020 to 2022). A major psychotic disorder characterized by abnormalities in the perception or expression of reality. "The purpose of this study was to assess the levels of serum IGF-2 and its binding proteins IGFBP-3 and IGFBP-7 in schizophrenia patients and the associations of these proteins with schizophrenia psychopathology and cognitive deficits." (PMID 32191705, 2020). "However, whether a change of IGF-2, IGFBP-3 and IGFBP-7 in patients is caused by schizophrenia itself or other confounding factors, for example, influenced by antipsychotic drugs, is still unknown." (PMID 32191705, 2020). "Insulin-like growth factor 2 (IGF-2) and IGF binding protein 7 (IGFBP-7) have been related to schizophrenia (SZ) due to their implication in neurodevelopment." (PMID 36076984, 2022). "Serum levels of the IGFBP7 gene product was found to be significantly lower in patients with schizophrenia compared to controls." (PMID 34573345, 2021). "Our paper indicates that there were much lower levels of serum IGF-2, IGFBP-3 and IGFBP-7 in Chinese schizophrenia patients." (PMID 32191705, 2020). "The schizophrenia patients had a much lower content of serum IGF-2, IGFBP-3 and IGFBP-7 than controls." (PMID 32191705, 2020).
stomach adenocarcinoma (3 papers, 2021 to 2025). "In stomach adenocarcinoma (STAD), the expression of IGFBP7 was significantly increased compared to that in normal tissues." (PMID 33531979, 2021).
acromegaly (2 papers, 2024 to 2025). Acromegaly is an acquired disorder related to excessive production of growth hormone (GH) and characterized by progressive somatic disfigurement (mainly involving the face and extremities) and systemic manifestations. "In our study, IGFBP7 was found to be higher in the acromegaly group than in the control group and showed high correlations with poor metabolic control parameters particularly HOMA-IR." (PMID 38709454, 2024). "In our study, IGFBP7 and CK18 were found to be higher in the acromegaly group than in the control group, supporting increased fibrosis and inflammation in the liver." (PMID 38709454, 2024). "Additionally, IGFBP7 (p = 0.048) and CK18 (p = 0.005) were higher in the acromegaly group than the control group." (PMID 38709454, 2024).
acute respiratory distress syndrome (2 papers, 2024 to 2025). Progressive and life-threatening pulmonary distress in the absence of an underlying pulmonary condition, usually following major trauma or surgery. "Furthermore, TIMP2*IGFBP7 was characterized by a high diagnostic value of AKI in patients with SARS-CoV2-associated acute respiratory distress syndrome." (PMID 39596140, 2024).
benign prostatic hyperplasia (2 papers, 2019 to 2020). A non-cancerous nodular enlargement of the prostate gland. "IGFBP7 has been detected in invasive prostate neoplasms compared to in normal secretory or benign prostatic hyperplasia." (PMID 30609749, 2019).
bipolar disorder (2 papers, 2022 to 2024). A disorder of the brain that causes unusual shifts in mood, energy, activity levels and the ability to carry out day-to-day tasks. "We calculated a linear regression model using the backpropagation method to predict the effects of independent variables such as the group (control and bipolar disorder) and age (years) over IGFBP-7 levels as dependent variables." (PMID 38720780, 2024).
brain tumors (2 papers, 2010 to 2022). "Similar to the in vivo data, the ex-vivo data at 24 h demonstrated a three- and six-fold increase in brain tumour signal for the anti-IGFBP7 sdAb compared with the competitively blocked anti-IGFBP7 sdAb-Cy5.5 and NC sdAb-Cy5.5, respectively." (PMID 20959824, 2010). "At 24 h after injection, brain tumour signal for the anti-IGFBP7 sdAb-Cy5.5 was three- and six-fold higher compared with competitively blocked anti-IGFBP7 sdAb-Cy5.5 and NC sdAb-Cy5.5, respectively." (PMID 20959824, 2010). "The results suggest that anti-IGFBP7 sdAb can be used to target appropriate contrast agents to abnormal tumour vasculature for non-invasive assessment of brain tumour angiogenesis using various imaging modalities." (PMID 20959824, 2010). "The anti-IGFBP7 sdAb-Cy5.5 homed to the brain tumour as early as 10 min after injection, with high signal in the tumour persisting up to 24 h after injection." (PMID 20959824, 2010). "In contrast, brain tumour signal in vivo was reduced at 4 and 24 h when animals were co-injected with the excess unlabelled anti-IGFBP7 sdAb." (PMID 20959824, 2010). "The results of the study suggest that anti-IGFBP7 sdAbs and anti-IGFBP7 sdAb-PEGylated-NPs are both promising molecular imaging agents for targeting brain tumour vessels with potential for clinical translation." (PMID 20959824, 2010). "The whole-body scans and ex vivo organ imaging at 72 h after injection demonstrated that the brain tumour signal of anti-IGFBP7 sdAb-PEGylated NPs-Cy5.5 is the highest compared with all other organs." (PMID 20959824, 2010). "By providing information on the degree of tumour angiogenesis and related clinical aggressiveness, the anti-IGFBP7 sdAb could also be used to assess/monitor efficacy of anti-angiogenic or other anti-tumour treatments, and thus improve the clinical management of brain tumours." (PMID 20959824, 2010). "In this study, anti-IGFBP7 sdAb PEGylated NPs displayed specific targeting to brain tumours compared with non-targeted PEGylated NPs." (PMID 20959824, 2010). "Organs (liver, kidney, spleen, lung, heart, brain and muscle) and extracted tumour biodistribution assessed by ex-vivo organ imaging 24 h after injection confirmed the selective brain tumour targeting of anti-IGFBP7 sdAb, but not NC sdAb." (PMID 20959824, 2010). "Using in vivo optical imaging, brain tumour selective targeting in mice was demonstrated for the anti-IGFBP7 sdAb-PEGylated-NPs-Cy5.5, in contrast to a non-targeted-PEGylated-NPs-Cy5.5." (PMID 20959824, 2010).
chronic heart failure (2 papers, 2022). "Finally, insulin-like growth factor-binding protein 7 (IGFBP-7) is a marker of myocardial damage that has been independently associated with chronic heart failure in AF patients." (PMID 35859587, 2022).
colitis (2 papers, 2021 to 2024). Inflammation of the colon. "As a secret protein, IGFBP7 contributed significantly to immune modulation of mosenchymal stromal cells in experimental colitis and was involved in the modulation of cytokine production by T cells." (PMID 33531979, 2021). "In a mouse experimental colitis model, intraperitoneally injected MSCs ameliorated the clinical and histopathological severity of induced colonic inflammation and restored the injured gastrointestinal mucosal tissues, while MSCs that were knocked down for IGFBP7 had minimal effects." (PMID 39045455, 2024). "The immunomodulatory properties of IGFBP7 were also demonstrated in an experimental colitis model." (PMID 39045455, 2024).